CLIC5 (CLIC family member 5)
Diseases named in the same sentence as CLIC5 in open-access papers:
CLIC5 is named in the same sentence as 40 diseases in open-access papers, as found by Europe PMC text mining. Sharing a sentence is not in itself a finding about the gene and the disease. The quoted sentences say what the papers report.
deafness (8 papers, 2012 to 2025). An inherited or acquired condition characterized by the complete loss of the ability to hear from one or both ears. "To address this, we investigated CLIC5, a gene linked to recessive deafness and vestibular dysfunction in humans and Clic5-deficient mice." (PMID 40859056, 2025). "These cells expressed several causal genes for various deafness forms, including Eps8l2, Gjb2, Gjb6, Homer2, Coch, Clic5, Dcdc2a, Pou3f4, Col4a6, and Six1." (PMID 37339214, 2023). "Twenty-five genes were present in both male and female hearing difficulty high variant load lists, including seven deafness genes (CLIC5, MYH14, COL9A3, ELMO3, FSCN2, GJB2, SLC26A5)." (PMID 35761239, 2022). "To consider the therapeutic potential for a hearing loss gene not previously explored, we investigated the gene encoding the chloride intracellular channel protein CLIC5, mutations in which lead to DFNB103 in humans and deafness and circling behavior in a Clic5-deficient mouse model." (PMID 40859056, 2025). "Two human families with loss-of-function CLIC5 mutations have been reported, with a total of five affected individuals who all suffer from nonsyndromic sensorineural hearing loss starting early in life and progressing to deafness by the second decade." (PMID 40885385, 2025). "Radixin and the ERM-interacting protein CLIC5 are expressed in hair cell stereocilia and loss of these proteins causes deafness, suggesting that an ELMO-ERM interaction may mediate actin cytoskeleton organization in hair cell stereocilia." (PMID 22558334, 2012). "Among a number of nonsyndromic deafness genes, variants in SLC26A4, COCH, MYO7A, GRHL2, and CLIC5 as well as POU4F3 are known to cause vestibular symptoms and/or dysfunction." (PMID 28545070, 2017). "In addition to GRXCR2 and taperin, several proteins linked to deafness are concentrated at or near the stereocilia base, including Fam65b, PTPRQ, CLIC5, radixin, and PDZD7." (PMID 30380417, 2018). "In “jitterbug” (jbg/jbg) mice, a partial deletion of CLIC5 exon 5 causes CLIC5A and CLIC5B proteins to be absent and results in progressive degeneration of inner ear hair cell sensory stereocilia with vestibular dysfunction at birth and eventual deafness." (PMID 40885385, 2025).
hearing loss (8 papers, 2018 to 2025). "Further, they provide a viable platform for modelling vestibular dysfunction, an often overlooked comorbidity that frequently occurs with inherited hearing loss, for example in association with mutations in CLIC5, COCH and ESPN." (PMID 36331565, 2022). "FOXI1, NF2, MYO15A and CLIC5 genes, were among others associated with swimming impairment and hearing loss." (PMID 34829759, 2021). "Here, we revealed an interaction between GRXCR2 and CLIC5, two proteins linked to hearing loss in humans." (PMID 34026762, 2021). "Taken together, we believe that CLIC5 gene therapy may be feasible in humans, as hearing loss in these individuals develops postnatally and progresses more gradually than that observed in Clic5−/− mice, potentially offering an expanded window of opportunity for treatment." (PMID 40859056, 2025). "The mechanism we present here, where GRXCR2 restricts taperin from entering the stereocilia shaft, may also explain the morphological defects and hearing loss caused by mutations of CLIC5, radixin, PTPRQ, MYO6, Fam65b, or other components located at the basal region of stereocilia." (PMID 30380417, 2018). "This study is the second report, worldwide, to describe CLIC5 involvement in human hearing impairment, and thus confirms CLIC5 as a novel non-syndromic hearing impairment gene that should be included in targeted diagnostic gene panels." (PMID 33114113, 2020). "Association of CLIC5 and SLC12A2 variants with hearing impairment in patients." (PMID 36035115, 2022). "Mutations in the human CLIC5 gene have been linked with progressive autosomal recessive, non-syndromic sensorineural hearing impairment with or without vestibular dysfunction and CLIC5 was found to be abundantly expressed in the fetal inner ear." (PMID 34685586, 2021). "Beyond the morphological changes caused by the absence of CLIC5, its deficiency has been shown to disrupt the localization of proteins such as RDX, TPRN, and PTPRQ, which are linked to hearing loss." (PMID 40859056, 2025). "In addition to CLIC5, only the CEP250 gene shows compound heterozygous synonymous variants that co-segregate with hearing impairment, which was unlikely to be the cause of the disease." (PMID 33114113, 2020).
hepatocellular carcinoma (3 papers, 2015 to 2023). A malignant tumor that arises from hepatocytes. "Studies show that the interactions of PODXL with ezrin and CLIC5 are associated with invasiveness and migration of Huh7 hepatocellular carcinoma (HCC) cell lines." (PMID 34201212, 2021). "CLIC5, Ezrin, and podocalyxin were overexpressed in hepatocellular carcinoma (HCC) and the inhibition of CLIC5 and podocalyxin resulted in decreased migration and invasion." (PMID 37371090, 2023). "In this study, we examined the expression of EZR, CLIC5 and PODXL at the mRNA and protein levels in a modified hepatocyte resistant model (MHRM) and in cases of human hepatocellular carcinoma (HCC)." (PMID 26135398, 2015).
COVID-19 (2 papers, 2022 to 2025). A disease caused by infection with severe acute respiratory syndrome coronavirus 2. "Signature genes associated with AT1 cells, including the reported YAP target genes AGER and CLIC5, were downregulated in COVID-19 patient lung samples." (PMID 40985618, 2025). "Consistently, proteomic and metabolomics data from CMs revealed several genes (KNG1, TXNIP, ITIH4, TIMP1, SERPING1/2/3, ITGA1, ADAR, and CLIC5 etc.)and molecules (adenosine and inosine) were related with platelet activation, thus, adding antiplatelet might be a possible therapeutic for COVID-19." (PMID 35903092, 2022).
glaucoma (2 papers, 2017 to 2021). Increased pressure in the eyeball due to obstruction of the outflow of aqueous humor. "Three genes, SRBD1, CLIC5, and KLHL36, have been found to be involved in immune responses and reported to be associated with various phenotypes, such as glaucoma, neurological disorders, and carcinoma." (PMID 28355295, 2017).
osteoarthritis (2 papers, 2022 to 2023). A noninflammatory degenerative joint disease occurring chiefly in older persons, characterized by degeneration of the articular cartilage, hypertrophy of bone at the margins and changes in the synovial membrane. "For clinical relevance, we extended our analysis to published data from knee synovial tissues of osteoarthritis patients, 28 29 which similarly showed that THY1-PRG4+CLIC5+ FLS exhibited SOX5, FOXO1 and CREB5 regulon activity." (PMID 36414376, 2023).
pancreatic ductal adenocarcinoma (2 papers, 2024 to 2025). An infiltrating adenocarcinoma that arises from the epithelial cells of the pancreas. "The role of CLIC5 expression has been shown to correlate with the prognosis of cancer, including lung adenocarcinoma, ovarian cancer, pancreatic ductal adenocarcinoma, etc.." (PMID 40785039, 2025). "Resistance to FOLFIRNOX in pancreatic ductal adenocarcinoma may result from MIR1307-induced reduction in CLIC5 expression." (PMID 38546385, 2024).
renal carcinoma (2 papers, 2015 to 2024). A carcinoma arising from the epithelium of the renal parenchyma or the renal pelvis. "The results of the TCGA-KIRC cohort showed that either in paired or unpaired renal cancer tissues, except for CLIC5, which was in a low expression state, the remaining four genes (MXD3, NUF2, PABPC1L, and PLK1) were in a high expression." (PMID 38546385, 2024). "The function of CLIC5 is proposed to be similar to that of EBP50, which is responsible for the interaction between EZR and PODXL in renal carcinoma." (PMID 26135398, 2015).
rheumatoid arthritis (2 papers, 2022 to 2025). A chronic, systemic autoimmune disorder characterized by inflammation in the synovial membranes and articular surfaces. "The changes in CLIC5 expression in HBEGF+ fibroblasts positively correlated with disease status and treatment response in rheumatoid arthritis." (PMID 40785039, 2025).
atrial fibrillation (1 paper, 2026). A disorder characterized by an electrocardiographic finding of a supraventricular arrhythmia characterized by the replacement of consistent P waves by rapid oscillations or fibrillatory waves that vary in size, shape and timing and are accompanied by an irregular ventricular response. "Previous studies have reported the involvement of CLICs (CLIC1, CLIC4, CLIC5) in atrial fibrosis and remodeling in atrial fibrillation (AF)." (PMID 41521401, 2026).
cardiac hypertrophy (1 paper, 2026). "The study findings further emphasized the possible roles of CLICs, particularly CLIC1, CLIC4, and CLIC5, in cardiac hypertrophy and heart failure." (PMID 41521401, 2026).
ciliopathy (1 paper, 2023). A genetic disorder of the cellular cilia or the cilia anchoring structures, the basal bodies, or of ciliary function. "Interestingly, we identified a novel cilia-related role for Clic5 by showing that Clic5b deficiency leads to a wide range of well-known ciliopathy-associated phenotypes." (PMID 37848494, 2023).
depression (1 paper, 2022). "cg00412337 in the nearby CLIC5 gene was also positively associated with depression." (PMID 36325427, 2022).
Hashimoto thyroiditis (1 paper, 2026). An autoimmune disorder caused by the production of autoantibodies against thyroid tissue. "This objective was to conduct Mendelian randomization (MR) analysis in order to investigate the potential causal relationship between chloride intracellular channel protein 5 (CLIC5) and Hashimoto thyroiditis (HT)." (PMID 41630298, 2026).
heart failure (1 paper, 2026). Inability of the heart to pump blood at an adequate rate to meet tissue metabolic requirements. "Among CLICs, CLIC1, CLIC4, and CLIC5 were significantly upregulated during the hypertrophic and heart failure phases of the TAC mouse model." (PMID 41521401, 2026). "Previous studies have reported the involvement of CLICs (CLIC1, CLIC4, and CLIC5) in AF, suggesting that these channels play a broader role in atrial remodeling beyond heart failure." (PMID 41521401, 2026). "We used single‐cell RNA‐seq to demonstrate the significant upregulation of CLIC1, CLIC4, and CLIC5 in a TAC mouse model and patients with DCM, underscoring their conserved roles in heart failure progression." (PMID 41521401, 2026). "Notably, the expression of CLIC5 mRNA significantly increased at day 3 post‐TAC and remained elevated throughout the hypertrophy and heart failure phases, indicating upregulation during disease progression." (PMID 41521401, 2026).
heart valvular diseases (1 paper, 2017). "The alterations of the chloride channels including CLIC1, CLIC4, and CLIC5 occur in both RNA-Seq and iTRAQ studies strongly support that the changes of chloride channels may play an important role in the pathophysiology of AF at least in heart valvular diseases." (PMID 28860555, 2017).
latent infection (1 paper, 2023). "On the other hand, the expression of lncRNAs lnc-XPNPEP1-5, lnc-CASKIN2-2, lnc-HSPA13-6, lnc-CLIC5-1, and LINC02502 was significantly reduced in both the latent infection group and the TB patient group compared to the uninfected HC group (all P-values < 0.05)." (PMID 38156018, 2023).
leukemia (1 paper, 2021). A malignant (clonal) hematologic disorder, involving hematopoietic stem cells and characterized by the presence of primitive or atypical myeloid or lymphoid cells in the bone marrow and the blood. "Moreover, this subset also shares leukemia and pro‐B gene expression signatures as well as high levels of the ETV6 target genes (BIRC7, WBP1L, CLIC5, ANGPTL2) with the ER subtype, indicating that these B‐other cases are the recently identified ER‐like subtype." (PMID 33987955, 2021).
liver cancer (1 paper, 2015). An epithelial or non-epithelial malignant neoplasm that arises from the liver. "In liver cancer, CLIC5 might play a similar role because the inhibition of CLIC5 decreases the migration and invasion of Huh7 cells." (PMID 26135398, 2015). "Our data demonstrated that EZR, CLIC5 and PODXL co-localization in the liver only occurs under the studied pathological conditions, suggesting that these proteins are potential biomarkers of liver cancer." (PMID 26135398, 2015).
lung carcinoma (1 paper, 2025). "For lung cancer, all manuscript-referenced genes were captured by either SHAP or LIME, with notable overlaps such as MYBL2, HYAL1, CLIC5, ADGRF5, and CLDN18." (PMID 40565055, 2025).
renal clear cell carcinoma (1 paper, 2024). "Similarly, CLIC5 expression was found to be lower than that of normal kidney tissues in renal clear cell carcinoma tissues extracted from our research center, while MXD3, NUF2, PABPC1L, and PLK1 were significantly higher in renal clear cell carcinoma tissues than in normal kidney tissues." (PMID 38546385, 2024).
sarcopenia (1 paper, 2025). Progressive decline in muscle mass due to aging which results in decreased functional capacity of muscles. "We found in this study that CLIC5 was downregulated in the database of patients with AP and sarcopenia." (PMID 40785039, 2025). "This study revealed for the first time that CLIC5 and SLC38A1 were shared biomarkers for AP and sarcopenia." (PMID 40785039, 2025). "In both test datasets (GSE149331 and GSE8479), the expression of CLIC5 and SLC38A1 was significantly downregulated in AP and sarcopenia, while the expression of C1QB was significantly upregulated." (PMID 40785039, 2025). "In conclusion, our study showed CLIC5 and SLC38A1 as shared genes of AP and sarcopenia in immune dysregulation and metabolic stress." (PMID 40785039, 2025). "Our study suggests the correlations of CLIC5 and SLC38A1 with AP and sarcopenia; nevertheless, we cannot deny that there are several limitations." (PMID 40785039, 2025). "The diagnostic value of CLIC5, SLC38A1 and C1QB was performed by receiver operating characteristic curves and the area under the curve in the datasets, and the validation results confirmed a consistent trend of downregulation of CLIC5 and SLC38A1 in AP and sarcopenia." (PMID 40785039, 2025).
Sepsis (1 paper, 2025). Sepsis is defined as life-threatening organ dysfunction caused by a dysregulated host response to infection. "In sepsis, CLIC5 was increased in sepsis‐induced myocardial injury and might play a role in regulating iron metabolism." (PMID 40785039, 2025).
vestibular disorder (1 paper, 2025). Pathological processes of the vestibular labyrinth which contains part of the balancing apparatus. "Here, we demonstrate that gene replacement therapy, using the utricle injection method, is a viable approach for treating hearing and vestibular disorders associated with Clic5 mutations." (PMID 40859056, 2025).
tumor (10 papers, 2014 to 2025). "Genes implicated in the modulation of tumor microenvironment and immunomodulation include CLIC5, RSAD2 and OASL." (PMID 40312750, 2025). "We identified five differentially expressed genes in both sets of mutated tumours (PBinomial = 1.5 × 10−8), including CLIC5 and IGF2BP1." (PMID 34753926, 2021). "The DNA methylation levels of the CLIC1–3 and CLIC5–6 promoters in tumor tissue with HCC were significantly lower in HCC tissues than in normal tissues." (PMID 34766585, 2021). "CLIC5 was detected in the cytoplasm of tumor region hepatocytes but was not expressed in controls and was only weakly expressed in non-tumor regions of livers from treated rats." (PMID 26135398, 2015). "Consistent with previous research results, we observed that the expression of CLIC1, CLIC3, and CLIC5 was increased in cancer tissues; the expression of CLIC1 and CLIC3 was associated with the progression of the tumor; and a lower expression of CLIC1 was associated with better OS in HCC." (PMID 34766585, 2021). "Further in-depth studies regarding the roles in the tumor process are required for CLIC5 and CLIC6." (PMID 32116799, 2020). "Similar to CLIC4, CLIC5 was also reported in mitochondria where it plays a role in modulation of ROS, which could also contribute to tumor signaling." (PMID 32116799, 2020). "Recently, two other genes (CLIC5 and MAMDC2) have also been reported to function as tumor suppressors in some cancers." (PMID 40535574, 2025). "PODXL, ezrin, and CLIC5 are colocalised in tumour regions of the rat liver, and PODXL and ezrin are present in immunoprecipitates of CLIC5." (PMID 34201212, 2021). "Although we observed co-localization of EZR, CLIC5 and PODXL in HCC samples, this expression pattern in tumor cells was only found in the late stage of HCC." (PMID 26135398, 2015). "Using GSTP as a marker for neoplastic lesions and tumors areas, EZR, CLIC5 and PODXL expression was co-localized within the tumor region of serial samples of rat liver tumors after 9, 12 and 18 months of treatment." (PMID 26135398, 2015). "The protein expression levels of EZR, CLIC5 and PODXL were higher in nodular and tumor areas compared to non-tumor areas or controls (p<0.05), which correlated with the qRT-PCR results." (PMID 26135398, 2015). "For example, three chloride intracellular channel genes (CLIC3, CLIC4, and CLIC5) were down-regulated, while CLIC6 was up-regulated three-fold in tumor tissues." (PMID 24466154, 2014). "CLIC5 and IGF2BP1 have been identified as markers of hyperdiploid ALL, however, none of the test tumours used in this analysis were hyperdiploid." (PMID 34753926, 2021). "Overexpression of EZR, CLIC5 and PODXL genes was observed in nodular (N) and tumor (T) areas but not in non-tumor (NT) areas and controls (C)." (PMID 26135398, 2015).
cancer (8 papers, 2010 to 2025). A tumor composed of atypical neoplastic, often pleomorphic cells that invade other tissues. "The results showed that TPX2 and BIRC5 were upregulated, while AGER, TEK, CLIC5, MAMDC2, EMCN, and SEMA3G were mostly downregulated in multiple cancer types." (PMID 40535574, 2025).
CLIC5 also shares sentences with these, for which no sentence is quoted: Hearing impairment (3 papers); breast carcinoma (2); gout (2); neurological disease (2); cerebellar ataxia (1); cyst (1); diabetes (1); Hydrocephalus (1); lung adenocarcinoma (1); membranous nephropathy (1); metabolic disorders (1); ovarian carcinoma (1); preeclampsia (1); Salmonella Infections (1).